MCIDAS (multiciliate differentiation and DNA synthesis associated cell cycle protein)
Description:
Transcription regulator specifically required for multiciliate cell differentiation. Acts in a multiprotein complex containing E2F4 and E2F5 that binds and activates genes required for centriole biogenesis. Required for the deuterosome-mediated acentriolar pathway. Plays a role in mitotic cell cycle progression by promoting cell cycle exit. Modulates GMNN activity by reducing its affinity for CDT1.
Synonyms: IDAS; MCI; MCIN; CILD42
Tractability: No criterion of Open Targets' tractability assessment is met for any kind of drug.
Gene: Protein-coding gene on chromosome 5 (55,219,564 to 55,227,315, reverse strand). Ensembl gene ENSG00000234602.
Subcellular location: Nucleus
Subcellular location (Human Protein Atlas): Nuclear bodies; Nucleoplasm
Gene Ontology:
Molecular function: identical protein binding; protein binding; transcription coregulator activity
Biological process: motile cilium assembly; positive regulation of DNA-templated transcription; regulation of cilium assembly; regulation of DNA-templated DNA replication initiation; regulation of mitotic cell cycle; centriole assembly; cilium assembly; multi-ciliated epithelial cell differentiation; positive regulation of transcription by RNA polymerase II; regulation of DNA replication
Cellular component: nuclear body; nucleolus; nucleoplasm; nucleus
Genetic constraint (gnomAD): Loss-of-function variants: 23 observed, 32.96 expected, observed/expected ratio (o/e) 0.7, 90% interval 0.5 to 0.99. The upper end of that interval is the gene's LOEUF score, 0.99, which puts it in group 4 of 6, group 1 being the genes least tolerant of losing a copy. Missense variants: 480 observed, 522.29 expected, observed/expected ratio (o/e) 0.92, 90% interval 0.85 to 0.99. Synonymous variants: 228 observed, 231.16 expected, observed/expected ratio (o/e) 0.99, 90% interval 0.88 to 1.1.
Gene-disease validity (ClinGen):
ClinGen rates the evidence that MCIDAS causes each of these diseases.
ciliary dyskinesia, primary, 42 (autosomal recessive): Definitive.
Homologues: Orthologues: chimpanzee MCIDAS (99% identical), macaque MCIDAS (95% identical), dog MCIDAS (88% identical), pig MCIDAS (86% identical), guinea pig MCIDAS (83% identical), rat Mcidas (79% identical), mouse Mcidas (78% identical), rabbit MCIDAS (75% identical), tropical clawed frog mcidas (50% identical), Drosophila melanogaster geminin (9% identical). Paralogues in human: GMNC (19% identical), GMNN (12% identical).
Diseases named in the same sentence as MCIDAS in open-access papers:
MCIDAS is named in the same sentence as 24 diseases in open-access papers, as found by Europe PMC text mining. Sharing a sentence is not in itself a finding about the gene and the disease. The quoted sentences say what the papers report.
Hydrocephalus (2 papers, 2024). Hydrocephalus is an active distension of the ventricular system of the brain resulting from inadequate passage of CSF from its point of production within the cerebral ventricles to its point of absorption into the systemic circulation. "While genetic mouse models of PCD frequently develop hydrocephalus, patients with PCD hydrocephalus are sporadic, except those with mutations in FOXJ1, CCNO, P73, and MCIDAS, indicating developmental differences between rodents and humans." (PMID 38032388, 2024). "Using the LPA-induced intracranial hydrocephalus mouse model, we demonstrated McIdas ability to convert periventricular cells into ependymal cells." (PMID 39468302, 2024). "In order to examine whether McIdas promotes cellular reprogramming towards the ependymal cell lineage in vivo, we have used our genetic mouse model of hydrocephalus which was previously established." (PMID 39468302, 2024). "In addition, forced expression of McIdas in both a genetic and an acquired hydrocephalus mouse model promoted in vivo reprogramming of cells residing in the ventricular walls of the diseased brain into functional ependymal cells." (PMID 39468302, 2024). "McIdas and GemC1 convert different cell types into ependymal cells both ex vivo and in vivo in hydrocephalic animal models, thus suggesting a new therapeutic intervention aiming at the regeneration of damaged ependymal cells in human hydrocephalus." (PMID 39468302, 2024). "To investigate whether McIdas would also reprogram cells in vivo, we used a mouse model of congenital hydrocephalus in which GemC1 has been inactivated, and a model of acquired hydrocephalus, triggered by intracranial hemorrhage." (PMID 39468302, 2024). "Our findings suggest that McIdas forced expression in human patients with hydrocephalus would contribute to the re-establishment of the SVZ niche leading to brain functions’ improvement by enhancing neuronal production in human patients with hydrocephalus and ameliorating brain function." (PMID 39468302, 2024). "Furthermore, we show that McIdas’ expression promotes ependymal cell regeneration in two different postnatal hydrocephalus mouse models: an intracranial hemorrhage and a genetic form of hydrocephalus and ameliorates the cytoarchitecture of the neurogenic niche." (PMID 39468302, 2024).
cancer (3 papers, 2018 to 2025). A tumor composed of atypical neoplastic, often pleomorphic cells that invade other tissues. "Eight genes were identified with SVs occurring in at least one cancer cat, with two genes found to impact only cancer individuals: ARAP1 and MCIDAS." (PMID 38580653, 2024).
tumor (3 papers, 2017 to 2025). "NOTCH suppresses multiciliation in tumor cells by inhibiting the expression of GMNC and MCIDAS, while Gmnc-Mcidas overexpression rescues multiciliation defects and suppresses tumor cell proliferation." (PMID 35322202, 2022).
infection (2 papers, 2020 to 2024). The state of being infected such as from the introduction of a foreign agent such as serum, vaccine, antigenic substance or organism. "At 5 days post infection, 86% of the McIdas-infected cells expressed FoxJ1 and showed accumulation of multiple basal bodies, based on Pericentrin immunostaining (Fig. EV4B,C)." (PMID 39468302, 2024). "Our analysis showed that 14 days post infection 49% of McIdas- and 19% of GemC1-infected astrocytes were expressing FoxJ1 (F and EV2D)." (PMID 39468302, 2024). "Moreover, our analysis revealed that 97% of the McIdas transduced cells were multiciliated 15 days following infection, based on acetylated α-tubulin and Pericentrin staining (Fig. EV3D,E)." (PMID 39468302, 2024). "To test this hypothesis, we conducted immunofluorescence experiments using a McIdas-specific antibody and quantified McIdas fluorescence in McIdas- and GemC1-infected astrocytes 7 days post infection." (PMID 39468302, 2024). "At the same time, ciliary markers such as DNAH5, DNAAF5, MCIDAS, and CCNO were downregulated following infection of hNECs." (PMID 33409274, 2020).
MCIDAS also shares sentences with these, for which no sentence is quoted: Infertility (3 papers); Alzheimer disease (2); neurodegenerative disease (2); adenoma (1); ciliopathy (1); congenital hydrocephalus (1); dementia (1); Hepatitis (1); intracranial hemorrhage (1); ischemia (1); ischemic stroke (1); liver steatosis (1); male infertility (1); mild cognitive impairment (1); Neonatal respiratory distress (1); nephritis (1); Obesity (1); primary ciliary dyskinesia (1); steatosis (1); Stroke (1).